PTH (parathyroid hormone)
Diseases named in the same sentence as PTH in open-access papers (continued):
Sharing a sentence is not in itself a finding about the gene and the disease.
adenoma (continued). "Having a maximum difference in jugular PTH of 15% in the failure group, values above this concentration could already be used as a reference for an estimate of probable adenoma laterality cutoff; however, considering the standard error of 10%, we estimated the cutoff value above 20%." (PMID 40209343, 2025). "SVS proved highly informative when it correctly lateralized pathological glands, with a PTH gradient consistently higher than the normal PTH level, thereby allowing the determination of potential anatomical quadrants in the neck where the adenoma might be located." (PMID 38541233, 2024). "Interestingly, larger parathyroid tumors secreted less PTH in relation to adenoma weight compared to the smaller tumors, which was confirmed in a small sub-set of parathyroid tumor cells large and small tumors, but no data was reported on vitamin D nutritional status of the study population." (PMID 36817587, 2023). "Giant PT adenomas (of more than 2–3 g) display a higher rate of bone complications in terms of brown tumors and osteitis fibrosa cystica which themselves are prone to post-PTX HBS, noting that usually the size of PT tumor associates with the levels of serum PTH." (PMID 37296804, 2023). "Furthermore, as PTH/Svol was negatively correlated with RI, a low RI may point to a more productive adenoma, while a high RI may propose a less effective one." (PMID 37892003, 2023). "The PTH per unit weight of the adenoma may be significantly lower in larger adenomas." (PMID 37892003, 2023). "Moreover, a greater awareness of this entity among surgeons and a wider use of intraoperative parathyroid hormone assay (ioPTH) which helps in finding the adenoma and terminating the operation, have driven in a continuous rise of its initial prevalence, as high as 15% in recent studies." (PMID 33845885, 2021). "In parathyroid cells, vitamin D inhibits PTH transcription and cell proliferation; a reduction of VDR activity, following the loss of menin, could represent a facilitation for the growth of parathyroid cells and adenoma development." (PMID 32326947, 2020). "It remains unclear if larger or smaller adenoma lead to a more extensive PTH spike." (PMID 30294345, 2018). "In assessing the success in identifying the adenoma side between imaging exams and jugular PTH collection, we observed high jugular MIBI and PTH hit rates, with statistical significance." (PMID 40209343, 2025). "After delivery, high parathyroid hormone (PTH) and calcium serum levels were found in Patient 2 and the scintigraphy showed the presence of adenoma of a parathyroid gland." (PMID 36232568, 2022). "MIBI scans are more likely to localize GPTA in patients with higher preoperative PTH and larger GPTA size; an adenoma correctly localized by MIBI has a 95% likelihood of weighing > 5.5 gm." (PMID 31722742, 2019). "The mean preoperative serum Ca level was 9.5 ± 0.36 mg/dL, the mean preoperative serum P level was 3.7 ± 1.4 mg/dL, and the mean preoperative serum PTH level was 53.7 ± 11.5 pg/mL in the patients without adenoma." (PMID 40104303, 2025). "A serum calcium level exceeding 14 mg/dL and PTH values greater than five times the normal level should raise suspicion of malignancy rather than adenoma." (PMID 40806850, 2025). "Although PTH-WO levels were higher in left inferior adenomas, this difference was not statistically significant." (PMID 41036141, 2025). "The parathyroid surgeon synthesizes these inputs to determine the extent of resection—focused parathyroidectomy for localized adenomas versus subtotal resection for multiglandular disease (e.g., MEN1 carriers)—aided by intraoperative PTH monitoring to confirm cure." (PMID 41210508, 2025). "Kruskal-Wallis test was performed to assess the difference in PTH level between various locations of adenomas due to the non-normal distribution of PTH values." (PMID 40445316, 2025).
adenoma (continued). "In concordance with immunohistochemistry results, Epfn gene expression was increased in the parathyroid gland and inversely decreased in the adenoma, while the expressions of PTH and CCND1 were upregulated, and interestingly, the expression of CaSR was diminished in the adenoma." (PMID 40164571, 2025). "Our study confirms that patients without adenoma detection on [18F]FCH PET/CT(MRI) had the lowest mean PTH values compared to those with single or multiple adenomas." (PMID 40445316, 2025). "Without the removal of the PTH secreting adenoma, the symptoms will reappear in the future, and thus any other forms of management will only be symptomatic relief for the time being." (PMID 39109312, 2024). "The adenoma size strongly correlated with PTH levels (rho=0.728, p<0.001) and PFi (rho=0.678, p<0.001), but PTH levels did not correlate with the corrected calcium levels (rho=0.206, p=0.114)." (PMID 39040613, 2024). "Although lateralisation was not obtained in Patient #2, significantly elevated PTH level was detected bilaterally in the level of inferior glands which was later explained with double adenoma (positive test)." (PMID 34688240, 2022). "Although parathyroid tumor cells were reported to generally express less PTH mRNA than normal in some studies, no genetic analyses were reported in those studies and it is unclear which, if any, adenomas were familial." (PMID 35038313, 2022). "In this study, a conversion to BNE was more often undertaken compared with the two other groups without localizing a second adenoma or MGD in patients with low basal PTH." (PMID 36515670, 2022). "In patient #12, although SVS indicated a positive increase in PTH in the left lower quadrant, no adenoma was found during the unilateral exploration." (PMID 34688240, 2022). "Pre-operative PTH-levels were higher in single adenomas detected by scintigraphy than in those not (p = 0.02)." (PMID 36261462, 2022). "Higher levels of PTH result in higher rates of distal colorectal adenoma and dysplasia in women but not in men42 and high levels of vitamin D were only protective for adenoma development in women but not in men41." (PMID 34493755, 2021). "For this reason, bilateral exploration should always be considered in cases of inadequate PTH decrease and adenoma size that can not explain high PTH values, even if imaging studies are strongly suggestive of single-gland disease." (PMID 33256695, 2020). "PTH in patients with PHPT is autonomously secreted by the abnormal parathyroid gland which may arise from hyperplasia, adenoma or carcinoma of the parathyroid glands." (PMID 31797261, 2020). "According to a large cohort study with > 340 patients, adenoma weight correlates with the percentage decrease in calcium levels from before to after surgery but not with the PTH decrease." (PMID 33256695, 2020). "Although adenoma weight was moderate correlated to preoperative PTH levels, it was not strong enough to be used in the estimation of adenoma weight." (PMID 33256695, 2020). "If serum PTH levels remain elevated with cinacalcet treatment in hypercalcemic recipients without adenoma, detailed imaging studies should be performed for enlarged glands." (PMID 32913586, 2020). "Hypertrophic parathyroid glands of these patients develop into hyperplasia or adenoma that is not affected by serum levels of calcium and autonomously secrete excessive PTH." (PMID 31879808, 2019). "Preoperatively high PTH, ALP, and UCa levels and large lesions with isoechoic or cystic appearances may be predictive of atypical adenoma or carcinoma in patients being evaluated for PHPT." (PMID 27901181, 2016). "Quick parathyroid hormone (QPTH) is a very helpful test in parathyroid surgery as the recording of a 50% drop from the preoperative parathyroid baseline level 10 min after excision, is a marker of successful adenoma excision (the Miami criterion)." (PMID 24685256, 2014).
adenoma (continued). "Extirpation of the adenoma no doubt stopped its PTH efflux into circulation, irrespective of a previous stepwise clamping." (PMID 24044556, 2013). "One patient in our study was found to have elevated serum PTH during follow up, despite appropriate Intraoperative PTH fall after excision of adenoma, but remains normocalcaemic and asymptomatic; hence, no further imaging has been deemed clinically necessary." (PMID 21197437, 2010). "In 2 patients (2,29%), the adenoma could not be found preoperatively while they were identified intraoperatively, after their removal the PTH decreased sufficiently and the calcium concentrations returned to normal." (PMID 36268338, 2022). "Multiple authors have shown variable degrees of correlation between serum parathormone (PTH) or/and calcium levels and adenoma weight, whereas other studies could not confirm these findings." (PMID 33256695, 2020). "We conclude that preoperative PTH levels may only serve as an approximate guide to adenoma weight, as direct preoperative prediction is not possible." (PMID 33256695, 2020). "Several studies could not demonstrate any relationship between serum calcium and PTH and adenoma weight, although these findings may be influenced from patients with hyperplasia, double adenomas and renal hyperparathyroidism, who were not excluded." (PMID 33256695, 2020). "Here we highlight that adenoma size is correlated to initial PTH levels but not initial calcium levels and that larger lesions are more likely to be symptomatic and therefore may need closer followup." (PMID 28003924, 2016). "A cohort of 617 patients (554 single adenoma (SA) and 63 MGD) was used to generate an idealised model that was embedded in software and installed in a laptop computer to enable intraoperative decision analyses, PTH curve plotting, and storage and transmission of data." (PMID 26542689, 2015). "We found no studies comparing PTH values of single-puncture jugular, only studies of selective jugular PTH collection through common femoral catheterization without comparing the concentration of the values, but with excellent results in the localization of adenomas." (PMID 40209343, 2025). "In one patient, the PTH levels increased and remained high for up to 30 minutes post excision, implying the presence of multiglandular disease; further neck exploration identified an ipsilateral second adenoma, not localised preoperatively by either ultrasound or sestamibi scan." (PMID 21197437, 2010).
hypovitaminosis D (176 papers, 2008 to 2025). "Hypovitaminosis D is both directly and indirectly linked to numerous aspects (menstrual/ovulatory irregularities, PTH elevation, obesity) of polycystic ovary syndrome, which is, in turn, associated with an increased risk of fractures." (PMID 40772111, 2025). "For rickets due to nutritional phosphorus deficiency, it is crucial to assess parathyroid hormone levels before initiating treatment." (PMID 40773440, 2025). "An increase in PTH, as seen in nutritional rickets and genetic disorders of vitamin D-dependent rickets (VDDRs), leads to chronic low serum phosphate, causing rickets." (PMID 37074534, 2023). "Hypovitaminosis D predisposes toward worsening lipid profiles through the actions of PTH, while serum PTH levels per se associate with higher glucose and LDL-C levels." (PMID 37447323, 2023). "The increasing PTH response to low vitamin D levels is important with respect to the Ca/P balance, and it causes demineralization to occur, as seen in cases of rickets and osteomalacia." (PMID 38813002, 2023). "These events, that is, Mg deficiency that leads to reduced 1,25(OH)2D synthesis and impaired PTH response, have been implicated in the described condition “Mg-dependent vitamin D-resistant rickets”." (PMID 36986033, 2023). "The pathophysiological mechanisms suggested for this association include the elevation of serum PTH levels—directly related to the reduction in 25(OH)D—and the deleterious effects of hypovitaminosis D on activation of the RAAS and endothelial function." (PMID 36771474, 2023). "Hypovitaminosis D is also known to correlate with higher inflammatory response, which together with increased PTH levels (a factor associated with multiple postoperative complications in HF patients and/or PMI significantly increases the risk of poor outcomes." (PMID 36431261, 2022). "This study aimed to estimate the prevalence of hypovitaminosis D in a healthy Tunisian population, and correlate the values with potential risk factors, and PTH levels." (PMID 35510205, 2022). "In people with CKD, hypovitaminosis D and increased serum PTH and FGF‐23 concentrations are associated with disease progression and decreased survival." (PMID 33128421, 2020). "While calciopenic rickets is associated with increased PTH concentrations, our patients with HR had normal or upper normal levels of PTH." (PMID 31514490, 2020). "Ultimately, the histological presence of osteomalacia defines the presence of pathology, and research should focus on how histology relates to levels of calcium deprivation, elevations of ALP and PTH, radiological signs of rickets and fracture risk." (PMID 28612338, 2017). "Collectively, excessive secretion of PTH and a hypophosphatemic state are crucial for establishment of vitamin D deficiency rickets." (PMID 26800885, 2016). "More importantly, induction of hypovitaminosis D causes significant fluctuations in parathyroid hormone (PTH) and mineral levels, complicating the interpretation of study results." (PMID 25815325, 2015). "This is an important finding, because the hypovitaminosis D can favor bone abnormalities and reduced bone mass and associated a significant increase in renal excretion and increased circulating levels of PTH, leading to typical feature of osteomalacia." (PMID 24864141, 2014). "Hypovitaminosis D in PTH-responders was associated with higher mortality than was the same condition in non-responders (P<0.05)." (PMID 24073266, 2013). "Hypovitaminosis D in PTH-responders is associated with higher APACHE II score and mortality than is the same condition in non-responders." (PMID 24073266, 2013). "We also found that hypovitaminosis D in PTH-responders is associated with higher APACHE II scores and mortality than was the same condition in non-responders." (PMID 24073266, 2013). "In our study, hypovitaminosis D in PTH-responders was associated with higher APACHE II scores than was the same condition in non-responders." (PMID 24073266, 2013).
hypovitaminosis D (continued). "An excess of phosphate levels can increase the signaling of PTH, causing resorption of bone, while a relative deficiency may lead to the development of rickets." (PMID 39062266, 2024). "Finally, PTH levels are expected to be markedly elevated in children presenting with rickets due to CKD, which is usually associated with elevated serum phosphate and creatinine levels." (PMID 34910242, 2022). "Results from this study suggest increased parathyroid hormone levels might be a better predictor of cardiovascular risk in patients with hypovitaminosis D." (PMID 36294836, 2022). "Consequently, there is a decreased synthesis of vitamin D in the epidermis stimulating parathyroid hormone secretion, and a higher risk of rickets." (PMID 35626880, 2022). "Subsequent studies in healthy population confirmed that increased body mass index (BMI) is associated to hypovitaminosis D, while body fat mass is inversely correlated to serum 25(OH)D levels and positively correlated to serum PTH levels in both adult and pediatric subjects." (PMID 34422722, 2021). "The results of these studies are more or less similar to our study in which high levels of PTH have been observed mostly in individuals with severe hypovitaminosis D. Interestingly, about 72% of participants with mild deficiency of vitamin D had normal PTH levels." (PMID 32821633, 2020). "It has been suggested that the variability of PTH levels in hypovitaminosis D may be due to concomitant magnesium deficiency." (PMID 30723655, 2018). "The goal of our study was to evaluate the prevalence of hypovitaminosis D and its determinants as well as PTH serum level determinants and associations of the 25-hydroxyvitamin D and PTH serum levels with MetS and its individual components in a sample of the Portuguese mainland population." (PMID 29149839, 2017). "This study showed a high national prevalence of hypovitaminosis D. The PTH levels showed a significant positive association with the WC component of MetS, and the VitD levels were negatively associated with the BP and triglycerides components as well as with the MetS." (PMID 29149839, 2017). "The goal of our study was to evaluate the prevalence of hypovitaminosis D and its determinants as well as PTH serum levels determinants and associations of the 25(OH)D and PTH serum levels with MetS and its individual components in a sample of the Portuguese mainland population." (PMID 29149839, 2017). "Furthermore, individuals with inefficient vitamin D stores have an increased risk of bone disorders like spondyloarthritis, rickets, and fractures due to higher bone resorption from an overproduction of parathyroid hormone (PTH)." (PMID 26288575, 2015). "However, the study did not report incidence of insufficient or deficient 25OHD levels, baseline PTH levels, data on postoperative vitamin D supplementation, or patient characteristics that were associated with hypovitaminosis D in this at risk population." (PMID 23724340, 2013). "In addition, hypovitaminosis D in PTH-responders was associated with higher APACHE II score and mortality than was the same condition in non-responders (P<0.05)." (PMID 24073266, 2013). "Parathyroid hormone (PTH) increases renal tubular calcium reabsorption and inhibits phosphorus reabsorption in order to maintain blood calcium levels, and ultimately, insufficient calcium phosphate products lead to systemic bone mineralization, causing rickets in children and osteomalacia in adults." (PMID 38449846, 2024). "Despite significantly elevated levels of parathyroid hormone and alkaline phosphatase, the blood phosphorus of the patient was decreased, suggesting that he had secondary rickets." (PMID 40420588, 2025). "In the 2016–2018 cohort, almost all cases normalized PTH levels after treatment with cholecalciferol ± calcium at doses used for nutritional rickets." (PMID 40709988, 2025).